MAML2 (mastermind like transcriptional coactivator 2)
Diseases named in the same sentence as MAML2 in open-access papers (continued):
Sharing a sentence is not in itself a finding about the gene and the disease.
Hashimoto thyroiditis (1 paper, 2025). An autoimmune disorder caused by the production of autoantibodies against thyroid tissue. "In contrast to thyroid SMECE which is a distinct entity arising in the background of fibrosing Hashimoto thyroiditis and lacking MAML2 gene alterations, salivary SMEC is a rare variant of MEC characterized by MAML2 gene break and/or CTRC1/CRTC3::MAML2 gene fusion." (PMID 39537991, 2025).
Human papillomavirus infection (1 paper, 2024). "Two genes, HLA-G and MAML2, were also significantly upregulated in the Human papillomavirus infection pathway." (PMID 38427106, 2024). "KEGG pathway visualization showed that UCKL1 and GSTT1 were upregulated in the drug metabolism pathway, and HLA-G and MAML2 were significantly upregulated in the human papillomavirus infection pathway." (PMID 38427106, 2024).
Hypertension (1 paper, 2017). The presence of chronic increased pressure in the systemic arterial system. "In summary, our work argues that Notch signaling provides a constant drive on expression of sGC in arterial smooth muscle and that this is perturbed by hypertension via reduction of the transcriptional coactivators MAML2 and FRYL." (PMID 28465505, 2017). "Up to this point our findings supported the view that NOTCH signaling provides a constitutive drive for aortic sGC expression in the mouse aorta that is disturbed by hypertension via repression of the coactivators MAML2 and FRYL." (PMID 28465505, 2017).
hypospadias (1 paper, 2019). Hypospadias is the displacement of the urethral meatus on the ventrum of the penis. "In patient 5, six variants in six genes were found: BNC2, FGF10, HSD3B2, IRX5, MAML2 and NOTCH2; all, except MAML2, have also been associated with hypospadias or gonadal development." (PMID 31555317, 2019).
mediastinal tumors (1 paper, 2023). "Recently, two additional patients with mediastinal tumors with YAP1::MAML2 rearrangements were reported that followed a more aggressive clinical course." (PMID 38067300, 2023).
papilloma (1 paper, 2024). A benign epithelial neoplasm that projects above the surrounding epithelial surface and consists of villous or arborescent outgrowths of fibrovascular stroma. "The loss of MAML2 expression in grade III and IV papillomas is higher than that in other grades, showing a progressive expression loss change." (PMID 38427106, 2024).
prediabetes (1 paper, 2025). "The NOTCH signaling pathway (hsa04330) was the only pathway shared between the prediabetes and T2D groups, with mastermind-like transcriptional coactivator 2 (MAML2) as the only shared gene." (PMID 41373473, 2025).
Stroke (1 paper, 2017). Sudden impairment of blood flow to a part of the brain due to occlusion or rupture of an artery to the brain. "Reduced expression of sGC, correlating with differential expression of MAML2, in stroke prone and spontaneously hypertensive rats was also seen, and RNA-Seq data demonstrated correlations between JAG1, NOTCH3, MAML2 and FRYL and the sGC subunits GUCY1A3 and GUCY1B3 in human coronary artery." (PMID 28465505, 2017).
vascular tumors (1 paper, 2024). "Another intriguing observation in vascular tumors is that TAZ::MAML2 may be found in EHE but that YAP::MAML2 is associated more with composite or retiform hemangioendotheliomas." (PMID 40491864, 2024).
tumor (65 papers, 2013 to 2026). "In 60-80% of cases, this tumor is associated with a specific genetic fusion CRTC1 or CRCT3::MAML2, which provides a molecular signature for diagnosis, but also has prognostic value, as MAML2-positive tumors are associated with a much better survival rate." (PMID 39677248, 2024). "Here, we performed a comprehensive review of MAML2 rearrangements encountered as part of our routine clinical testing experience, including the frequency across all tested tumor types and diagnostic performance in MEC and ASC." (PMID 35457138, 2022). "Specific epidermoid, mucous, and intermediate tumor cells, and MAML2 fusion testing, are essential to avoid potential diagnostic pitfalls." (PMID 36147445, 2022). "MECs also consist of glandular and squamous components; however, their diagnosis requires a tumour originating from peribronchial minor salivary glands, and/or a classic low‐grade component, and/or the presence of a MAML2 rearrangement." (PMID 39311155, 2025). "Zhang and colleagues suggested that testing for the MAML2 gene via fluorescence in situ hybridization can identify Warthin’s tumour-like MEC and prevent cytological misdiagnosis." (PMID 39658893, 2025). "A rearrangement of mastermind-like transcriptional coactivator 2 (MAML2) (11q21) gene was identified in the tumor cells by fluorescence in situ hybridization." (PMID 40677284, 2025). "Despite the common MAML2 fusion partner, the corresponding fusion genes vary based on the tumor subtype in which they occur." (PMID 38067300, 2023). "Ki-67 proliferation index was about 5%; FISH detection showed that there was a broken rearrangement of MAML2 gene in the tumor cells." (PMID 37144989, 2023). "Ki-67 proliferation index was about 5%; periodic acid Schiff staining was positive in mucoid cells; FISH detection showed that there was a broken rearrangement of MAML2 gene in the tumor cells." (PMID 37144989, 2023). "The proliferation index of Ki-67 was about 20%; FISH detection showed that there was a broken rearrangement of MAML2 gene in the tumor cells." (PMID 37144989, 2023). "It manifested that the restrained tumor growth owing to LINC01152 depletion was partly reversed by inhibited miR-466 but completely recovered by upregulated MAML2." (PMID 33483471, 2021). "It has to be emphasized that this study is the largest reported screening of Warthin tumours by means of break apart FISH to detect the MAML2 rearrangement." (PMID 32222825, 2020). "A cluster of Mastermind-like (MAML) genes, including MAML1, MAML2, and MAML3, encodes transcriptional co-activators for various signal pathways such as Notch signaling and tumor suppressor pathway activated in multiple cancers." (PMID 28249600, 2017). "Although MAML2 gene rearrangement is observed in some cutaneous HAs, its significance in breast HA remains unclear." (PMID 41624218, 2026). "Such a low percentage of MAML2 fusion may be attributed to technical challenges in a tumor with a low number of neoplastic cells." (PMID 39537991, 2025). "MAML2 rearrangement was identified in the tumor cells using FISH." (PMID 40677284, 2025). "In addition, MAML2 gene fusion is more common in low-to-intermediate-grade MEC, suggesting a low risk of tumor recurrence and metastasis, as well as a favorable prognosis." (PMID 40677284, 2025). "MAML2, a tumor suppressor gene with high methylation modification but loss of protein expression, and NRGN, a tumor gene with low methylation modification but upregulated protein expression, can be used as biological indicators to judge the malignant transformation of SNIP-SCC." (PMID 38427106, 2024). "No molecular markers have been found associated with this tumor, except for the negative MAML2 rearrangement." (PMID 37305870, 2023). "However, MAML2 rearrangements were observed in a subpopulation of cells in the squamous areas of 2 of 8 metaplastic WTs and in 5 of 15 metaplastic WT-like neoplasms in other studies." (PMID 36752878, 2023).
tumor (continued). "Notably, despite the inclusion of the MAML2 status as a distinguishing feature in the WHO tumor classification, studies comparing the frequency of MAML2 rearrangements in MEC and ASC are limited." (PMID 35457138, 2022). "It was suggested that more MAML2 expressed in GBM tissues compared to adjacent non-tumor ones." (PMID 33483471, 2021). "In addition, we screened a consecutive series of 114 Warthin tumour cases by means of MAML2 break apart fluorescence in situ hybridization to assess its value in differential diagnosis." (PMID 32222825, 2020). "Indeed, a prognostic classification recently proposed in the first-line setting of advanced PSCC receiving cisplatin-based chemotherapy included one clinical factor, visceral disease, and one tumor tissue molecular factor, MAML2 gene expression." (PMID 28066240, 2016). "Subsequently, compared with non-neoplasia nasal epithelial tissues, the expression of HLA-G and NRGN was upregulated in grade I, II, III and IV tissues, while the expression of MAML2 was lost." (PMID 38427106, 2024). "In this manner, elevated γ-secretase activity and MAML2 expression induced higher NOTCH1 signalling in PCa cells, which increased tumor cells proliferation and invasion." (PMID 36439868, 2022). "The five included studies that investigated MAML2 rearrangement in both -MEC and ASC in the same tumor set examined a total of 88 MEC and 110 ASC in pancreas, salivary glands, lung, cervix and thymus." (PMID 35871081, 2022). "Previous studies have reported that the CRTC1/MAML2 fusion protein induces the activation of the Notch signaling pathway in the MEC, resulting in enhanced cell proliferation and tumor development." (PMID 35012286, 2021). "This is in line with the finding of recurrent chromosomal translocations in MEC and ACC involving the MAML2 and MYB genes, respectively, which appear to play a key role in the molecular pathogenesis of these neoplasms." (PMID 26053092, 2015). "In summary, the current study demonstrated that MAML2 rearrangement is a frequent event in PMEC and specific to this tumor as compared with primary lung ASC." (PMID 24714697, 2014). "We validated the tumor origin by immunocytochemistry and revealed high expression for MUC 1, MAML2 and an absence for smooth muscle actin." (PMID 25229469, 2014). "Our results together with previous data from a smaller series did solidly indicate that MAML2 rearrangement occurs commonly and is exclusively seen in PMECs, suggesting that it may be a functional marker to facilitate diagnosis and differential diagnosis for this tumor." (PMID 24714697, 2014). "To characterize the expanded mucoepidermoid tumor cells, we confirmed the tumor lineage trace by MUC 1 and MAML2 expression before (passage 3) and after (passage 12+5) cell sort." (PMID 25229469, 2014). "MAML2 rearrangement was detected in all cases by FISH, suggesting it may be a defining feature of breast HA." (PMID 41624218, 2026). "By contrast, ASC is, by definition, a high‐grade tumour; does not originate from minor salivary glands; and does not have MAML2 rearrangements." (PMID 39311155, 2025). "Using tumor samples collected from the Lgr5-specific Ythdf1cki mouse model, qPCR analysis revealed that YTHDF1 knock-in increased the expression of NOTCH1 downstream targets, including MAML1, MAML2, HES1, and HEY1." (PMID 41423446, 2025). "Four tumors originally diagnosed as MEC were MAML2 gene rearrangement negative and were classified as one high-grade tumor and three low- or intermedia-grade tumors according to their typical morphological features." (PMID 38429827, 2024). "A negative result for MAML2 rearrangement is less informative, as both tumor types can be negative, which limits the potential diagnostic value of this test." (PMID 35871081, 2022). "The investigation of MAML2 status is particularly advised when Warthin tumour is considered in a young, non-smoking, female patient." (PMID 32222825, 2020).
tumor (continued). "MAML2 is present in 50% of cases of MEC and it is specific to this tumor." (PMID 27994904, 2016). "MAML2 rearrangement appears frequent in PMEC and specific with this tumor." (PMID 24714697, 2014). "Furthermore, four of 11 MEC cases (36.4%) were MAML2 fusion-negative, comprising one low-grade, two intermediate-grade and one high-grade tumor." (PMID 38429827, 2024). "This raises the possibility that tumors classified as high-grade MECs are actually ASC or another tumor, yet to be defined; however, low grade MECs may also be negative for MAML2 rearrangement." (PMID 35871081, 2022). "Knockdown of MAML2 significantly affected cell colony formation in vitro, the knockdown of EMP1, IRS2, and SP100 did not affect tumor growth or metastasis." (PMID 40781158, 2025). "Worse overall survival was associated with higher pT stage, higher TNM stage, residual tumors, greater tumor size, high grade tumor histology, and absence of CRTC1::MAML2 fusion." (PMID 38067300, 2023).
cancer (38 papers, 2015 to 2026). A tumor composed of atypical neoplastic, often pleomorphic cells that invade other tissues. "Furthermore, loss of fitness in response to MAML2 knockout is unique to MAML2-fused cell lines in the three cancer types where the fusion is observed." (PMID 31097696, 2019). "To elucidate the mechanisms by which YM fusion promotes cancer cell proliferation and survival, we conducted an RNA sequencing (RNA-seq) analysis to compare gene expression between YM/MAML2-depleted (shM2-3) and control (shCtl) ES-2 cells." (PMID 39624057, 2024). "Given the therapeutic indications for a diagnosis of MEC (a malignant neoplasm), MAML2 rearrangement should be confirmed in suspected cases of central MEC." (PMID 37082423, 2023). "For example, AOAH (a lipase acyloxyacyl hydrolase) and MAML2 (a transcriptional coactivator in the NOTCH-signaling pathway) are commonly downregulated in all cancers." (PMID 37024957, 2023). "Of these, 143 neopeptides were derived from clonal mutations, with two originating from cancer driver genes (GPC3 and MAML2)." (PMID 35410325, 2022). "Data obtained through the chromatin-immunoprecipitation technique provided information about the presence of histone marks at MAML2 in cancer cells but its occupancy reduced considerably in resveratrol-treated cancer cells." (PMID 29495357, 2018). "For example, YAP::MAML2, a fusion protein found across multiple cancer types, results from a local chromosomal inversion, which may be more common than fusions resulting from translocations." (PMID 40491864, 2024). "The Mastermind-like 2 (MAML2) gene, encoding a transcriptional activator of the Notch signalling pathway, has been implicated in cancers, but has no known function in the nervous system." (PMID 37672513, 2023). "Additionally, epidemiological studies have confirmed that polymorphisms in MAML2, a NOTCH pathway gene, were related to cancer susceptibility and prognosis." (PMID 31652449, 2019). "To investigate the role of the YM fusion in regulating cancer cell malignancy in vitro, we employed short hairpin RNAs (shRNAs; shM2-1 and shM2-3) targeting the 3′ UTR and TAD sequences of the fusion/MAML2, respectively." (PMID 39624057, 2024). "These TFs regulate critical genes (such as MAML2, CDK6, FAM84B and PTBP1) that play fundamental roles in cancer." (PMID 33537074, 2021). "Other gene fusions involving transcription factors include NUT (or NUTM1), POU5F1, MAML2, NFIB, PLAG1, TFE3, NOTCH, and PAX8 fusions, imparting spatially and/or stochastically dysregulated expression in multiple different cancer types." (PMID 26684754, 2015). "Four proteins identified in the faecal proteome are potential biomarkers of the cancer, including diacylglycerol kinase (DGKB, DGK), mastermind-like transcriptional coactivator 2 (MAML2), structural maintenance of chromosomes 4 (SMC4), IG domain-containing protein and transglutaminase 2 (Tgm2)." (PMID 35202347, 2022). "In addition, recurrent breakpoints of SVs targeting cancer genes commonly occurred in frequently deleted regions, e.g., CDKN2A on 9p21.3, MAML2 and ATM on 11q21-22, RAD51B, and TRAF3 on 14q 24-32.3, CYLD and NLRC5 on 16q12.1-13." (PMID 34234122, 2021). "Therefore, our study indicated that it was necessary to distinguish PMEC and MEC-like carcinoma by a combination with morphology, immunostains, such as TTF-1, and MAML2 rearrangement." (PMID 26575266, 2015). "FISH analysis revealed no MAML2 gene rearrangement in all 8 MEC-like carcinomas and confirmed that the nature of the MEC-like carcinoma is different from PMEC." (PMID 26575266, 2015).
cardiovascular disease (1 paper, 2017). "We find that both MAML2 and, albeit to a lesser extent, FRYL have the capacity to independently drive sGC expression, making them potential targets for prevention of cardiovascular disease caused by an elevated blood pressure." (PMID 28465505, 2017).
head and neck tumors (1 paper, 2022). "Analysis by primary site showed that the majority of MAML2 rearranged cases were found in head and neck tumors (n = 18/23, 78.3%) with an overall frequency of 5.86% (n = 18/307)." (PMID 35457138, 2022). "The prevalence of MAML2+ across all tumors was 0.28% (n = 23/8106) and the majority of MAML2+ cases were found in head and neck tumors (78.3%), where the overall prevalence was 5.9% (n = 18/307)." (PMID 35457138, 2022).
MAML2 also shares sentences with these, for which no sentence is quoted: porocarcinomas (8 papers); squamous cell carcinoma (4); head and neck carcinoma (3); hidradenoma (3); clear cell carcinoma (2); diabetes (2); lung carcinoma (2); myoepithelial carcinoma (2); myoepithelioma (2); nasopharyngeal carcinoma (2); pulmonary mucoepidermoid carcinoma (2); salivary carcinomas (2); skin cancer (2); thymic tumor (2); acute lymphoblastic leukemia (1); adamantinoma (1); astrocytoma (1); bladder cancer (1); breast (1); breast mucoepidermoid carcinoma (1); carcinoma in situ (1); cervical cancer (1); cervical squamous cell carcinoma (1); chondrosarcoma (1); chronic lymphocytic leukemia (1); cylindroma (1); depression (1); endocervical adenocarcinoma (1); eosinophilia (1); epithelial-myoepithelial carcinoma (1).
A further 31 diseases each share a sentence with MAML2 in 1 paper.